IL24 (interleukin 24)
Diseases named in the same sentence as IL24 in open-access papers (continued):
Sharing a sentence is not in itself a finding about the gene and the disease.
endometriosis (continued). "However, the percentages of IL-24–producing plasmablasts were significantly higher in women with stage IV endometriosis (p < 0.05) compared with those in the control group." (PMID 40607413, 2025). "Based on our findings, we speculate that IL-24–producing cells with a regulatory phenotype are involved in the pathogenesis of endometriosis." (PMID 40607413, 2025). "They demonstrated that monocyte-derived macrophages from healthy women and co-cultured with the eutopic endometrium of women with endometriosis downregulated IL-24 production and its receptor expression (calculated as MFI) compared to endometrial stromal cells cultured alone." (PMID 40607413, 2025). "In our study, we aimed to assess whether regulatory cells in their most “natural” state produce IL-24 and whether endometriosis is characterized by altered IL-24 expression." (PMID 40607413, 2025). "We investigated specific subpopulations of B lymphocytes, namely Bregs, to determine their ability to produce IL-24 and whether their percentages varied in women suffering from endometriosis." (PMID 40607413, 2025). "Furthermore, the percentage of IL-24–producing plasmablasts was significantly higher in women with endometriosis (p < 0.01), although the percentage of IL-24–producing plasmablasts among CD19-CD38hiCD27int cells or their IL-24 expression levels (MFI) was similar in both groups." (PMID 40607413, 2025). "In the context of endometriosis, IL-24–driven inflammatory signaling may intensify local immune activation, contribute to the persistence of ectopic endometrial lesions, and disrupt the structural integrity of surrounding tissues, including the peritoneum and reproductive organs." (PMID 40607413, 2025). "Therefore, it is tempting to speculate the induction in IL-24+ Tregs observed in our study might have enhanced adverse immune tolerance in endometriosis." (PMID 40607413, 2025). "The significance of this cytokine secretion by regulatory cells is unclear, but we speculated that IL-24 may enhance the improper immunosuppressive activity of Tregs and plasmablasts in endometriosis, which enables the implantation and growth of endometrial lesions outside the uterus." (PMID 40607413, 2025). "Women with endometriosis showed a higher percentage of IL-24–producing Tregs (CD4+CD127-CD25hiFOXP3+IL-24+), IL-24–producing Tregs among CD4+ cells, and among Tregs in comparison to controls (both p < 0.05)." (PMID 40607413, 2025). "(2016), which reported reduced IL-24 expression in the eutopic and ectopic endometrium of women with endometriosis compared with women without the condition." (PMID 40607413, 2025). "Nonetheless, we observed an increase in IL-24+ Tregs percentage in women with endometriosis, regardless of endometriosis stages." (PMID 40607413, 2025). "Therefore, we investigated whether Tregs and several subpopulations of Bregs at different developmental stages can produce IL-24 upon PMA/ionomycin stimulation and whether their percentages are altered in patients with endometriosis." (PMID 40607413, 2025).
fibrosarcoma (3 papers, 2012 to 2022). A malignant mesenchymal fibroblastic neoplasm affecting the soft tissue and bone. "In conclusion, we have established a spontaneous feline fibrosarcoma cell line and have identified the combinatorial use of Ad.Ras-DN, Ad.Rb and CTV-Mda7/IL-24 genes as a possible future adjuvant treatment for this case of feline fibrosarcoma." (PMID 22666387, 2012). "Investigations on the anti-tumor activity of MDA-7/IL-24 and its potential to modulate pro-immune Th1 responses in a murine syngenic model of fibrosarcoma highlighted IL-24 as a potent cytokine in inhibiting tumor growth and triggering the regression of tumor cells." (PMID 35752792, 2022). "We also tested the effects of two immunostimolatory human cytokines (Mda-7/IL-24, and IFN-γ) that were transferred and expressed into the feline fibrosarcoma cells using adenoviruses." (PMID 22666387, 2012). "The observed tumor cell killing effects were stronger when we transduced the feline fibrosarcoma cells with CTV-Mda7 than with IFN-γ, possibly due to the previously demonstrated Mda-7/IL-24 higher pro-apoptotic ability." (PMID 22666387, 2012).
Hypertension (3 papers, 2015 to 2022). The presence of chronic increased pressure in the systemic arterial system. "IL-24 also regulates the expression of inflammation- and hypertension-related genes, such as angiotensinogen, endothelin-1, ATRAP and PDGF in H2O2 treated MOVAS cells." (PMID 27271601, 2016). "Overall, these studies suggest that IL-24 may be a novel therapeutic target for cardiovascular disease and/or hypertension." (PMID 27271601, 2016). "However, the role of IL-24 on the pathogenesis of hypertension was seldom studied." (PMID 26517713, 2015).
keloid (3 papers, 2020 to 2025). An irregularly shaped, elevated mark on the skin caused by deposits of excessive amounts of collagen during wound healing. "Adenovirus-mediated human interleukin 24 selectively suppresses proliferation and induces apoptosis in keloid fibroblasts." (PMID 39799030, 2025). "In this study, treatment with the replication-incompetent adenovirus vector carrying IL-24 gene selectively suppressed proliferation and induced apoptosis in keloid fibroblasts." (PMID 39799030, 2025). "Adenovirus-mediated IL-24 selectively inhibited the proliferation and induce apoptosis of KFs, suggesting that IL-24 has great potential in therapy of keloid." (PMID 33959031, 2021). "IL-24 mRNA in keloid fibroblasts was obviously lower than in normal skin." (PMID 39799030, 2025). "Thus, IL-24 has tremendous potential as a gene therapy for keloids and may lead to new gene therapeutics and provide a means of enhancing the therapeutic applications for keloid therapy." (PMID 39799030, 2025). "It was reported that the IL-24 gene might be involved in the formation of keloids." (PMID 39799030, 2025). "The formation of keloid may be correlated with the down-regulation of IL-24." (PMID 33959031, 2021).
liver diseases (3 papers, 2020 to 2025). "IL-24 was identified via bioinformatics in patient datasets and validated in metabolic dysfunction-associated steatotic liver disease (MASLD) patient sera." (PMID 41288708, 2025). "Conclusively, we uncovered that cytosolic IL-24 is critical for protecting ER stressed hepatocytes from death, which may be a good diagnostic and therapeutic target for clinical liver diseases." (PMID 31907348, 2020). "The demonstrated hepatoprotective effects of IL-22 in liver diseases suggest that its homologous cytokine IL-24 also possesses therapeutic potential." (PMID 41288708, 2025). "Second, given prior evidence indicating limited therapeutic effects of exogenous IL-24 protein in liver diseases, this study adopted an endogenous overexpression strategy." (PMID 41288708, 2025). "Given the abundant IL-24 expression in the normal mouse or human liver detected in our preliminary experiments, the role of hepatocyte IL-24 in liver diseases has yet to be deciphered." (PMID 31907348, 2020). "This may provide a potential therapeutic opportunity for UPR-related human liver diseases, especially those with low hepatocyte IL-24 expression." (PMID 31907348, 2020). "Although no literature has shown so far that PLAU, FGF5, and IL24 affect HIRI by regulating immune cell infiltration, studies have reported the important regulatory roles of these two genes in the immune microenvironment and immune response in liver disease." (PMID 40705804, 2025).
non-small cell lung carcinoma (3 papers, 2015 to 2021). A group of at least three distinct histological types of lung cancer, including non-small cell squamous cell carcinoma, adenocarcinoma, and large cell carcinoma. "In addition, the co-administration of IL24-iRGD led to significantly increased apoptotic events in non-small cell lung cancer cells compared with the single treatment of IL24." (PMID 32847045, 2020).
spondyloarthropathy (3 papers, 2016 to 2024). A group of inflammatory rheumatic diseases associated with arthritis and enthesitis, and often involving the axial skeleton. "Drawing parallels with studies in RA and spondyloarthropathy, where IL24 is elevated in plasma and synovial cells, reinforces the notion of IL24 as a common factor in autoimmune joint disorders." (PMID 38792924, 2024).
stomach cancer (3 papers, 2011 to 2025). "On the other hand, PPAR β/δ activation causes pro-inflammatory changes in a number of systems, including IL-8 and IL1β induction in macrophages, and massive inflammatory changes in gastric tumors caused by PPAR β/δ activation, including IL1, IL6, IL24 induction." (PMID 22606335, 2012).
uveitis (3 papers, 2021 to 2025). An inflammatory process affecting a part of or the entire uvea. "Subsequently, our group confirmed the expression of IL-24 by induced Th17 cells in vitro, as well as uveitogenic Th17 cells from the animal model of uveitis, experimental autoimmune uveitis (EAU)." (PMID 35054813, 2022). "Our subsequent research confirmed that Th17 cells expressing IL-17 can trigger a negative feedback loop that promotes the production of the inhibitory cytokine IL-24 through the activation of NFKB signaling pathway, which is crucial for controlling uveitis." (PMID 40072803, 2025). "However, IL-24 seems to play a protective role in other autoimmune and inflammatory diseases—at least in animal studies, such as IBD, MS, uveitis, and liver fibrosis." (PMID 35054813, 2022). "The exact functions of IL-10, IL-24, and TGF–β in relation to Th17 cells in EAU are ripe for further investigation, holding the promise of uncovering new therapeutic targets that could finely tune these cytokines to effectively manage uveitis." (PMID 40072803, 2025). "However, clinical trials targeting IL-17A in uveitis have not been successful, which might be because the IL-17A-targeted drug improved EAU by inducing IL-24 in vivo, but silencing IL-24 in Th17 cells enhanced the disease." (PMID 34795583, 2021).
breast tumor (2 papers, 2012 to 2025). "The replication of CNHK600-IL24 in breast tumor cells and fibroblasts were assessed by TCID50 and MTT assay; the secretion of IL-24 was measured by ELISA and western blotting." (PMID 22640485, 2012). "Our in vitro and in vivo observations demonstrated that oncolytic adenovirus expressing IL-24 can actively destroy breast tumor and significantly prolong survival." (PMID 22640485, 2012).
Burkitt lymphoma (2 papers, 2024 to 2025). A rare form of malignant mature B-cell non-Hodgkin lymphoma. "According to clinical data, IL24 was observed to be downregulated in tumor tissues, and low IL24 expression was determined to be a prognostic indicator of poor outcomes in Burkitt lymphoma patients." (PMID 38737469, 2024).
Cirrhosis (2 papers, 2020 to 2021). A chronic disorder of the liver in which liver tissue becomes scarred and is partially replaced by regenerative nodules and fibrotic tissue resulting in loss of liver function. "Nonetheless, serum IL-24 was undetectable in CCL4-treated mice and human cirrhosis and ALF patients, excluding its engagement as a “hepatokine” in UPR condition." (PMID 31907348, 2020). "Clinically, we observed a concomitant downregulation of IL-24 and upregulation of CHOP in the cirrhosis and ALF tissues as compared with the healthy liver." (PMID 31907348, 2020).
colonic diseases (2 papers, 2025). "Summarizing these results, we identified 5 proteins (CCL20, CXCL1, CXCL11, HGF, and IL-24) with increased abundance in colonic diseases, irrespective of the disease entity (colonic CD and UC) that significantly correlated with both, tissue gene expression and inflammatory severity." (PMID 40291692, 2025).
influenza (2 papers, 2023 to 2025). An acute viral infection of the respiratory tract, occurring in isolated cases, in epidemics, or in pandemics; it is caused by serologically different strains of viruses (influenzaviruses) designated A, B, and C, has a 3-day incubation period, and usually lasts for 3 to 10 days. "While IL24 expression has been shown following PM exposure and demonstrates antiviral activity, neither PM nor influenza alone induced IL24 at either 2 or 24 hours, suggesting potentially elevated antiviral activity through IL-24-mediated priming through mechanisms such as TLR3-mediated apoptosis." (PMID 40671793, 2025).
leishmaniasis (2 papers, 2024). Infectious disease that is transmitted through the bite of hematophagous female phlebotomine sand flies. "In the context of leishmaniasis, the biological role and expression pattern of IL-24 is poorly studied, with one preprint report showing elevated levels of IL-24 in CD274+ and IDO1+ myeloid cells in human CL skin lesions." (PMID 39364404, 2024). "However, biologic actions and expression patterns of IL-24 are rather understudied in leishmaniasis, and based on the role of IL-24 in wound healing, it can be reasonable to consider a protective effect for IL-24 in CL." (PMID 39639867, 2024).
lupus (2 papers, 2013 to 2024). "The gene cluster that includes interleukin 10 (IL10), IL19, IL20 and IL24 is located on chromosome 1q31-32, a genomic region that is linked with susceptibility to systemic lupus erythematosus (SLE, OMIM 152700)." (PMID 24130510, 2013).
measles (2 papers, 2016 to 2024). A highly contagious viral infection caused by the measles virus. "Interestingly, we previously identified IL-24 (IL24) along with CD93 as markers of differential MV-specific transcriptional response (in PBMCs) in 15 high vs. 15 low antibody responders to measles vaccination." (PMID 38633249, 2024).
prostate tumor (2 papers, 2015 to 2019). "This was confirmed by expression of MDA-7/IL-24 followed by cell death in CaP sections from the Hi-Myc mice that lead to diminished prostate tumor size, all of which were further enhanced by BI-97D6." (PMID 25926554, 2015).
renal carcinoma (2 papers, 2021 to 2022). A carcinoma arising from the epithelium of the renal parenchyma or the renal pelvis. "The conclusion of a WT1/IL-24 regulatory axis indicates the importance of WT1 in regulating the renal cancer microenvironment." (PMID 35915803, 2022). "This study provides the first evidence that WT1 overexpression induces G2/M cell cycle arrest via upregulating IL-24 expression and inhibits human renal carcinoma cell proliferation." (PMID 35915803, 2022). "It is well known that IL-24 is an inflammatory cytokine closely involved in renal cancer progression." (PMID 35915803, 2022). "The findings suggest that the WT1/IL-24 regulatory axis may be essential as a regulator of cell proliferation and may thus represent an attractive target for renal carcinoma prevention and treatment." (PMID 35915803, 2022). "Consequently, HDAC inhibitors have also been reported to work synergistically with MDA7/IL-24 in killing renal carcinoma cells and glioblastoma." (PMID 35008495, 2021).
squamous cell carcinoma (2 papers, 2016 to 2018). A carcinoma arising from squamous epithelial cells. "A loss of tumorigenic potential of squamous cell carcinoma cells could be due to the upregulation of the melanocyte differentiation associated gene IL-24." (PMID 27387763, 2016). "One of these signaling routes employs IL-24 as an autocrine messenger, which contributes to reducing the tumorigenicity and proliferative potential of the former squamous cell carcinoma cells." (PMID 27387763, 2016).
acute liver failure (1 paper, 2020). Rapid deterioration of liver function causing encephalopathy and coagulopathy. "In a clinical setting, patients with acute liver failure manifested a profound decrease of hepatic IL-24 expression, which was associated with disease progression." (PMID 31907348, 2020). "To examine the biological significance of IL-24 in clinical situations, we collected liver tissue and serum samples from 9 healthy donors, 9 patients with liver cirrhosis and 22 patients with acute liver failure (ALF)." (PMID 31907348, 2020).
acute promyelocytic leukemia (1 paper, 2019). An aggressive form of acute myeloid leukemia (AML), characterized by arrest of leukocyte differentiation at the promyelocyte stage, due to a specific chromosomal translocation t(15;17) in myeloid cells. "Taken together, our data suggested that chimeric oncolytic adenovirus AdCN306-IL-24 could express IL-24 gene, representing a potential therapeutics for acute promyelocytic leukemia." (PMID 31145345, 2019).
acute renal failure (1 paper, 2020). "We also demonstrated the increased renal expression of Il19, Il20, and Il24 in an I/R-induced rat model of acute renal failure and in the STZ-induced rat model of diabetic nephropathy, as well." (PMID 32306980, 2020). "The mRNA expression of Il19, Il20 and Il24 increased in the kidney of rats with I/R-induced acute kidney injury and in the kidney of diabetic rats as well." (PMID 32306980, 2020).
allergic asthma (1 paper, 2022). A asthma with a basis in a pathological type I hypersensitivity reaction. "Subsequent work in the same group found that upper-airway IL-24, an IL-4-induced epithelial type 2 cytokine, could be used as a proxy for lower-airway IL-24 to diagnose allergic asthma." (PMID 36032162, 2022).
allergic rhinitis (1 paper, 2022). Inflammation of the nasal mucous membranes caused by an IgE-mediated response to external allergens. "An elevated level of IL-24 was reported in the nasal secretions of patients with allergic rhinitis and was reduced by allergen-specific immunotherapy, suggesting an association between IL-24 and the pathogenesis of allergic rhinitis." (PMID 35054813, 2022).
ameloblastoma (1 paper, 2017). The most common odontogenic tumor, arising from the epithelial component of the embryonic tooth and usually affecting the molar-ramus region of the mandible or maxilla. "Nevertheless, in our study the expression of IL-24 was not significantly up-regulated in ameloblastoma (FC 1.25 p-value = 0.6), however further studies are called for to investigate the whither or not miR205 act as an angel or a devil in the pathogenesis of ameloblastoma." (PMID 27965463, 2017).
autoimmune uveitis (1 paper, 2022). An autoimmune form of uveitis (disease). "This study highlights the potential of IL-24 as a promising therapeutic agent for autoimmune uveitis." (PMID 36233291, 2022). "This study sheds new light on IL-24 as a potential therapeutic candidate for autoimmune uveitis." (PMID 36233291, 2022). "This suggests that IL-24 may be pathogenic in other types of tissue inflammation, not making it an ideal candidate for the systemic treatment of autoimmune uveitis, which is usually a manifestation of active systemic autoimmune diseases." (PMID 36233291, 2022). "To explore the potential of IL-24 as a therapeutic agent in CNS autoimmunity, we induced experimental autoimmune uveitis (EAU) in wildtype mice and intravitreally injected IL-24 into the inflamed eye after disease onset." (PMID 36233291, 2022). "In order to better evaluate IL-24 as suitable as a long-term treatment for autoimmune uveitis, future studies in EAU should be carried out with longer observation and multiple doses of IL-24 injection." (PMID 36233291, 2022). "Therefore, we intravitreally injected recombinant IL-24 into the inflamed eyes of EAU mice and demonstrated that it is capable of suppressing ocular inflammation, supporting its potential as a local treatment for patients with autoimmune uveitis." (PMID 36233291, 2022).
autoinflammatory syndrome (1 paper, 2022). A group of disorders of the innate immune system characterized by attacks of seemingly unprovoked inflammation without significant levels of either autoantibodies or autoreactive T cells more characteristic of autoimmune disease. "demonstrate that PKR drives induction of type I IFN response in proteasome associated autoinflammatory syndromes depending on its cytosolic interactor IL-24 accumulation." (PMID 36275769, 2022).